MAPK8 (mitogen-activated protein kinase 8)
Diseases named in the same sentence as MAPK8 in open-access papers (continued):
Sharing a sentence is not in itself a finding about the gene and the disease.
neuroblastoma (47 papers, 2011 to 2025). Neuroblastoma (NB) is the most common solid, extracranial childhood tumor. "Using neuroblastoma xenograft models, we establish CNR2 and MAPK8 as promising candidates for the treatment of high-risk neuroblastoma." (PMID 31900415, 2020). "The role of MAPK8/JNK1 is less well understood, although it has been linked to neuroblastoma progression." (PMID 31900415, 2020). "Together, these data provided an independent set of data to support the potential of a CNR2 agonist against neuroblastoma, and encourage investigation to define MAPK8 (JNK1) inhibitors with improved toxicity profile as a future direction." (PMID 31900415, 2020). "The finding that a CNR2 agonist GW405833 and a MAPK8 inhibitor AS601245 were active in neuroblastoma cells, motivated experiments to evaluate their on-target selectivity." (PMID 31900415, 2020). "Based on our in vivo results, we propose that MAPK8 partly regulates neuroblastoma growth." (PMID 31900415, 2020). "Most of our predictions, including the CNR2 inhibitor GW405833, the UGCG inhibitor DL-PDMP, the TSPO antagonist PK11195, and the MAPK8/JNK inhibitor AS601245, downregulated the expression of genes induced during the cell cycle, implicating effects on neuroblastoma cell growth." (PMID 31900415, 2020). "The three compounds with anti-neuroblastoma effect (AS601245, JNK-IN-8 and SP600125) have higher affinity for MAPK8 than at least one of the other isoforms, while CC-930 has a 12-fold lower affinity for MAPK8 than the other isoforms." (PMID 31900415, 2020).
steatosis (47 papers, 2011 to 2025). Increased lipid within the cytoplasm of cells. "In the MAPK/ERK/JNK pathway, JNK1 (also known as MAPK8) is known to promote the development of steatosis and inflammation." (PMID 30871035, 2019). "Moreover, after the treatment with the association, the increment in the expression of the genes related to cell survival, AKT1, MAPK8, PIK3CA (four times), and FAS (eight times), and to anti-inflammatory signaling, IL10 (four times), was observed in respect to the steatosis control." (PMID 36770927, 2023).
Stroke (46 papers, 2010 to 2025). Sudden impairment of blood flow to a part of the brain due to occlusion or rupture of an artery to the brain. "We showed that the expression of Dlg4, Gria1, Grin2a, Gng3, Gnb5, MapK8, and Bdnf (encoding PSD-95, GluA1, GluNMDA2A, G-protein subunit gamma 3, G-protein subunit beta 5, JNK, and BDNF, respectively) was strongly reduced 1 week after stroke." (PMID 31888302, 2019).
multiple myeloma (41 papers, 2008 to 2024). "Both the PSMC6 and MAPK8 genes were upregulated in melanosis coli patients, and CRISPR Genome-Wide Screening demonstrated that the PSMC6 subunit is an important and sensitive target for bortezomib in multiple myeloma cells." (PMID 34329194, 2021).
asthma (36 papers, 2005 to 2025). "Using Gromacs-2022.04, we simulated the molecular dynamics (MD) of a 100 ns protein-ligand complex for EGFR, ALB, MAPK8, ESR1, and SRC, respectively, which are typical core targets for allergic rhinitis and asthma." (PMID 37781715, 2023). "In this study, we constructed the PPI network; IL6, CASP3, EGFR, MAPK8, ESR1, CCND1, and PPARG were found to be the core genes of YPF in treating asthma." (PMID 36105239, 2022).
non-small cell lung carcinoma (36 papers, 2010 to 2026). A group of at least three distinct histological types of lung cancer, including non-small cell squamous cell carcinoma, adenocarcinoma, and large cell carcinoma. "Autophagy mediated by MAPK8/9/10 could be repressed by Rabl3, leading to poor survival of non-small cell lung cancer." (PMID 31508368, 2019). "Furthermore, circular RNA CircTADA2A has been reported to enhance MAPK8 expression by acting as a miR-214-3p sponge and an EIF4A3 decoy, thereby promoting invasion and migration in non-small cell lung cancer cells." (PMID 41318488, 2025).
depression (35 papers, 2015 to 2026). "MAPK8 responds to various extracellular stimuli, including stress and cytokines, regulating gene expression implicated in inflammation and neuronal plasticity, thereby modulating depression and anxiety." (PMID 38835657, 2024). "In this module, ADCYAP1R1, PRKACA, MAPK8, MAPK14, GRIA1, and FOS are both targeted genes of CGFC and pathogenic genes of depression; RHOA is a specific targeted gene of CGFC, and most of these genes are related to the pathogenesis or treatment of depression." (PMID 34867413, 2021). "In PPIN, the main hubs such as AKT1, JUN, MAPK8 and STAT3 have already been reported to be involved in depression." (PMID 28954415, 2017).
myocardial infarction (33 papers, 2008 to 2025). Gross necrosis of the myocardium, as a result of interruption of the blood supply to the area, as in coronary thrombosis. "MAPK signaling pathway plays a vital role in the pathogenesis of cardiovascular diseases, for example, MAPK8 was identified as the target gene in myocardial infarction." (PMID 36624378, 2023).
oral cancer (32 papers, 2015 to 2025). "The down-regulation of MAPK8/JNK1 is reported to reduce human oral cancer cell migration by inhibiting MMP-9 enzymatic activity." (PMID 32703964, 2020). "The most common genes involved in the top 10 pathways were MAPK1, MAPK8, MAPK14, and IL6 which were seen to be associated with the MAPK signaling pathway which may be the key pathway through which andrographolide may aid in treating oral cancer." (PMID 39229580, 2024). "The predominant genes implicated in the ten principal pathways were MAPK1, MAPK8, MAPK14, and IL6, which were observed to be linked to the MAPK signaling pathway, perhaps serving as the critical channel through which Galangin may facilitate the treatment of oral cancer." (PMID 39702881, 2024).
COVID-19 (30 papers, 2020 to 2024). A disease caused by infection with severe acute respiratory syndrome coronavirus 2. "A recent network pharmacology approach revealed the novel therapeutic targets of COVID-19 inflammation, including MAPK8 (JNK1), MAPK10 (JNK3), and BAD (Bcl-2-associated death promoter), which are involved in the RAS signaling pathway and autophagy." (PMID 36293117, 2022). "Mitogen-activated protein kinase 14 (MAPK14), angiotensin-converting enzyme (ACE), toll-like receptor (TLR4), and MAPK8 are the main players that are directly linked to the majority of the phytocompounds and played a major role in COVID-19-associated pathways." (PMID 36144690, 2022). "MAPK14, ACE, TLR4, and MAPK8 genes are present in all the compounds, and these genes are associated with COVID-19 pathways." (PMID 36144690, 2022). "Investigations have suggested that MAPK14 and MAPK8 should be considered as potential new targets for COVID-19 treatment." (PMID 39130417, 2024). "In summary, the activation of IGFR-I and enhanced NOTCH signaling, coupled with altered expression of Bcl2, AKT1, and MAPK8 in severe COVID-19 may lead to an environment that favors cell survival and proliferation." (PMID 39502570, 2024). "The underlying mechanisms of kaempferol against COVID-19/PF co-occurrence may be related to bind to EGFR, SRC, MAPK3, MAPK1, MAPK8, AKT1, RELA and PIK3CA." (PMID 35754492, 2022). "Similar to the EGFR state observed in mild COVID-19, we also detected altered expression of Bcl2, AKT1, and MAPK8." (PMID 39502570, 2024). "According to the results of cytoscape, the targets of JFBDS for treating COVID-19 mainly contained EGFR, PIK3CA, lymphocyte-specific protein tyrosine kinase (LCK), mitogen-activated protein kinase 1 (MAPK1), MAPK3, MAPK8, STAT3, TNF, IL2 and RELA." (PMID 35165507, 2022). "Further bioinformatic analysis revealed 8 core targets (EGFR, AR, ESR1, MAPK8, MDM2, EZH2, ERBB2 and MAPT) in the VitD-COVID-19-osteoporosis network." (PMID 36307516, 2022). "Bioactive compounds in this plant target the significant COVID-19 responsible receptors such as MAPK14, ACE, TLR4, and MAPK8, which makes this plant an ideal candidate for treating this deadly infection." (PMID 36144690, 2022). "TNF, GAPDH, MAPK3, MAPK1, EGFR, CASP3, MAPK8, mTOR, IL-2, and MAPK14 are important targets for YQS in COVID-19 treatment." (PMID 35340244, 2022). "The main active ingredients of AE against COVID-19 were quercetin, kaempferol and luteolin, and the important targets were IL-6, MAPK1, MAPK8, IL-1β, and RELA." (PMID 33658066, 2021). "Our research suggests that BAD-Indomethacin's inhibition with the other two hub proteins, MAPK8-6MNA, MAPK10-Rofecoxib might play cumulative actions by inactivating the RAS signaling pathway against COVID-19." (PMID 33953223, 2021). "In this study, 44 potential targets were obtained through the intersection of the disease targets of COVID-19 and the action targets of AE, which are mainly related to inflammatory or immune factors, such as IL-6, MAPK1, MAPK8, IL1B, RELA, CXCL-8, CCL2, and PTGS2." (PMID 33658066, 2021). "Finally, IL-6, MAPK3, MAPK1, MAPK14, MAPK8, IL-1β, CCL2, EGFR, PPARG, and NOS2 were declared key targets of XFBD for COVID-19." (PMID 35185537, 2021). "The result suggested that the three NSAIDs' key mechanism against COVID-19 might be to inhibit inflammation of lung cells by inactivating the RAS signaling pathway, and blockers of MAPK8, MAPK10 and BAD might suppress cytokine storm." (PMID 33953223, 2021). "Employing the molecular docking and systems network pharmacological strategies to uncover the molecular mechanisms, anti-SARS-CoV2/COVID-19 effects of these potential bioactive molecules could be shown to be altered by key bioactives and some corresponding genes such as MAPK14, ACE, TLR4, and MAPK8." (PMID 36144690, 2022).
triple-negative breast carcinoma (26 papers, 2016 to 2025). An invasive breast carcinoma which is negative for expression of estrogen receptor (ER), progesterone receptor (PR), and human epidermal growth factor receptor 2 (HER2). "The MAPK8 inhibitor JNK-IN-8 has demonstrated therapeutic potential, since it synergizes with lapatinib to induce cell death in triple-negative breast cancer (TNBC) cells and significantly improves survival in mouse models with TNBC xenografts." (PMID 40468448, 2025).
Anxiety (25 papers, 2012 to 2026). Intense feelings of nervousness, tension, or panic often arise in response to interpersonal stresses. "Therefore, we speculate that ACG can affect stress-induced anxiety behavior by regulating MAPK8." (PMID 35624976, 2022). "In our study, 17 core common targets of ACG and anxiety were predicted, of which ESR1, SRC, AKT1, MAPK8, EGFR, and MMP9 belong to the prolactin and estrogen signaling pathways." (PMID 35624976, 2022).
psoriasis (24 papers, 2013 to 2026). An autoimmune condition characterized by red, well-delineated plaques with silvery scales that are usually on the extensor surfaces and scalp. "In order to determine the role of JNK1 signaling pathway in skin inflammation, we evaluated the sensitivity of Mapk8-/- mice to repeated topical applications of Aldara®, a classical model that shares many features with human psoriasis." (PMID 33613525, 2020).
osteoporosis (23 papers, 2017 to 2026). A condition of reduced bone mass, with decreased cortical thickness and a decrease in the number and size of the trabeculae of cancellous bone (but normal chemical composition), resulting in increased fracture incidence. "The colored target details of the MAPK pathway—ERK (MAPK1), JNK(MAPK8), and p38 (MAPK14)—are three classical cascades of the MAPK pathway, all of which were involved in the potential mechanism of AB–DA treating osteoporosis." (PMID 37849727, 2023).
metabolic syndrome (22 papers, 2010 to 2025). A cluster of metabolic risk factors for CARDIOVASCULAR DISEASES and TYPE 2 DIABETES MELLITUS. "It was noted that CPT-1 and GLP-1 were also associated with MAPK8; this implies that FOE is also involved in the metabolic syndrome signaling pathway." (PMID 38794679, 2024).
Hepatitis (21 papers, 2010 to 2024). Inflammation of the liver. "Our study found that the MAPK8 rs17780725 AA genotype may increase the risk of low response to hepatitis B vaccines." (PMID 29898681, 2018). "Meanwhile, we observed that in hepatitis-related HCC, patients with higher expression of BCL2L1, EGFR, ESR1, HNF4A, MAPK8, and PTEN, and lower expression of HDAC1 had a better clinical prognosis." (PMID 36133813, 2022).
skin cancer (17 papers, 2010 to 2025). "For example, in a mouse skin cancer model, MAPK8-deficient mice developed a greater number of papillomas." (PMID 40369663, 2025).
acute myeloid leukemia (15 papers, 2010 to 2025). Acute myeloid leukemia (AML) is a group of neoplasms arising from precursor cells committed to the myeloid cell-line differentiation. "Beyond CRC, PARP14 contributes to tumorigenesis in B-cell lymphoma by inhibiting JNK1 (MAPK8) signaling, thereby preventing apoptosis, and in acute myeloid leukemia by enhancing glycolysis to support cancer cell proliferation." (PMID 40741921, 2025).
epilepsy (13 papers, 2019 to 2025). A brain disorder characterized by episodes of abnormally increased neuronal discharge resulting in transient episodes of sensory or motor neurological dysfunction, or psychic dysfunction. "Collectively, our analysis suggested DElncRNAs might promote caspase-dependent apoptosis through MAPK8/JNK signaling pathway in the course of epilepsy, which have been confirmed by several previous studies in epileptic rat models." (PMID 34867172, 2021).
acute lymphoblastic leukemia (11 papers, 2015 to 2025). Leukemia with an acute onset, characterized by the presence of lymphoblasts in the bone marrow and the peripheral blood. "In addition, pro-survival SOX4-dependent upregulation of JNK1 (MAPK8) was demonstrated as a critical factor in acute lymphoblastic leukemia." (PMID 29423023, 2018).
Hyperinsulinemia (11 papers, 2010 to 2025). An increased concentration of insulin in the blood. "Insulin itself can create a positive feedback loop by activating ATF2 in this pathway solely or mediated by MAPK8 (preceded by MAP4K4) or PRKCE which can eventually lead to hyperinsulinemia." (PMID 32993798, 2020).
oral squamous cell carcinoma (11 papers, 2010 to 2026).
pneumonia (9 papers, 2006 to 2023). An acute, acute and chronic, or chronic inflammation focally or diffusely affecting the lung parenchyma, caused by an infection in one or both of the lungs (by bacteria, viruses, fungi, or mycoplasma.). "Compared with the model group, isorhamnetin reduced the protein expressions of SYK, IL-6, MAPK14, MAPK8, TNF-α, AKT, p-Akt, PIK3CA, EGFR and IL-1β in lung tissues of pneumonia mice." (PMID 36506534, 2022).
tauopathies (9 papers, 2011 to 2025). "AP-1 itself might be induced by MAP kinases, as suggested by the simultaneous increase in the GA of MAPK8/JNK1 and protein levels of MAP3K8/TPL-2 in (pTau +) astrocytes of both tauopathies." (PMID 35976433, 2022).
influenza (8 papers, 2015 to 2025). An acute viral infection of the respiratory tract, occurring in isolated cases, in epidemics, or in pandemics; it is caused by serologically different strains of viruses (influenzaviruses) designated A, B, and C, has a 3-day incubation period, and usually lasts for 3 to 10 days. "For example, TNF has immune regulatory, proinflammatory, and anti-viral functions, MAPK8 modulates lymphocyte homeostasis, IL10 is generally considered to be an anti-inflammatory cytokine, but production of IL-10 has also been shown to be detrimental during high-dose primary influenza challenge." (PMID 32754224, 2020).
chronic obstructive pulmonary disease (7 papers, 2017 to 2024). A chronic and progressive lung disorder characterized by the loss of elasticity of the bronchial tree and the air sacs, destruction of the air sacs wall, thickening of the bronchial wall, and mucous accumulation in the bronchial tree. "PGF and its downstream MAPK8 and MAPK14 signaling pathways are potential therapeutic targets for the treatment of emphysema and chronic obstructive pulmonary disease (COPD)." (PMID 28642633, 2017).
gouty arthritis (5 papers, 2018 to 2024).
Huntington disease (5 papers, 2008 to 2023). Huntington disease (HD) is a rare neurodegenerative disorder of the central nervous system characterized by unwanted choreatic movements, behavioral and psychiatric disturbances and dementia. "One gene (MAPK8) was reported to be directly associated with Huntington's disease." (PMID 22162763, 2011). "The gene MAPK8 was reported to be involved in Huntington's disease and the genes WIF and CSNK2A2 are known to participate in the Wntpathway which was reported to be linked to HD." (PMID 22162763, 2011).
lipid metabolism disorders (5 papers, 2021 to 2025). "MAPK8 is related to lipid metabolism, and lipid metabolism disorder is an important risk factor for the occurrence of DN." (PMID 34621904, 2021).
dry eye (4 papers, 2018 to 2024). "JUN and MAPK8 can affect the symptoms of xerostomia and xerophthalmia in SS patients by regulating the expression of AQP5." (PMID 38728503, 2024). "MAPK8 (JNK1) was also investigated in a mouse model of dry eye, showing an increased level of phosphorylated JNK1/2 in the corneal and conjunctival epithelia." (PMID 30374345, 2018).
endometriosis (4 papers, 2014 to 2023). The growth of functional endometrial tissue in anatomic sites outside the uterine body. "Two studies have demonstrated MAPK8 activity in endometriosis and this was linked to increased inflammatory responses." (PMID 25207642, 2014).
hepatitis B (4 papers, 2015 to 2022). "The MAPK8 rs17780725 AA genotype seems to be associated with low response to hepatitis B vaccines, but it has not yet reached significance (P = 0.083)." (PMID 29898681, 2018).
Intellectual disability (4 papers, 2014 to 2020). "Furthermore, loss of function mutations of SLAIN1 (as well as of MAPK8, which was also identified as zDABM-protein in our screening) are associated with intellectual disability." (PMID 28882895, 2017).
sarcoma (4 papers, 2012 to 2023). A usually aggressive malignant neoplasm of the soft tissue or bone. "Analysis using the U133Plus gene expressions expands this result by including JUN (JUN oncogene), MAPK8 (mitogen activated protein kinase 8), SRC (v-SRC sarcoma) and FYN (FYN oncogene related to SRC) as protein kinases within dasatinib’s discriminating genes." (PMID 23056181, 2012).